LMNA (lamin A/C)
Diseases named in the same sentence as LMNA in open-access papers (continued):
Sharing a sentence is not in itself a finding about the gene and the disease.
familial dilated cardiomyopathy (17 papers, 2009 to 2024). A a genetic form of heart disease that occurs when heart (cardiac) muscle becomes thin and weakened in at least one chamber of the heart, causing the open area of the chamber to become enlarged (dilated). "Variants (pathogenic) of the LMNA gene are a common cause of familial dilated cardiomyopathy (DCM), which is characterised by early-onset atrioventricular (AV) block, atrial fibrillation and ventricular tachyarrhythmias (VTs), and progressive heart failure." (PMID 39204134, 2024). "The LMNA gene is the second most commonly mutated gene in familial dilated cardiomyopathy (DCM), accounting for 5% to 8% of cases." (PMID 36899919, 2023). "Mutations in the LMNA gene are detected in around 5% of patients affected by non-familial dilated cardiomyopathy, 5–10% of patients with familial dilated cardiomyopathy and 33% of cases of familial dilated cardiomyopathy with conduction system defects." (PMID 33923914, 2021). "LMNA mutations are thought to be among the most common causes of familial dilated cardiomyopathy, accounting for approximately 10%." (PMID 32954377, 2020). "In conclusion, to our knowledge, this is the first comprehensive report on abnormalities in AFM-derived mechanical properties of cardiomyocytes expressing a LMNA mutation associated with a severe form of familial dilated cardiomyopathy (LMNA D192G)." (PMID 26323789, 2015). "We identified an autosomal dominant non-sense mutation (R225X) in exon 4 of the lamin A/C (LMNA) gene in a Chinese family spanning 3 generations with familial dilated cardiomyopathy (DCM)." (PMID 23362510, 2012). "Lamin A/C (LMNA) gene mutations are a known cause of familial dilated cardiomyopathy, but the precise mechanisms triggering disease progression remain unknown." (PMID 32313136, 2020). "The last group of patients in our present study was the group of familial dilated cardiomyopathy patients (PLN/LMNA group) who had a genetic disorder affecting the genes LMNA and PLN." (PMID 29305677, 2018). "LMNA E161K was identified in an individual with familial dilated cardiomyopathy." (PMID 21179469, 2010). "Many of these diseases arise due to mutations in LMNA, such as autosomal dominant Emery-Dreifuss muscular dystrophy (AD-EDMD) and familial dilated cardiomyopathy (DCM), which predominantly affect muscle." (PMID 19855837, 2009).
limb-girdle muscular dystrophy (16 papers, 2013 to 2026). Limb-girdle muscular dystrophy (LGMD) is a heterogeneous group of muscular dystrophies characterized by proximal weakness affecting the pelvic and shoulder girdles. "Mutations in EMD and LMNA also cause limb girdle muscular dystrophy." (PMID 31430335, 2019). "LMNA encodes the protein lamin A/C which forms part of the nuclear lamina, and mutations have been linked to many other disorders such as Charcot-Marie-Tooth neuropathy, progeria syndromes, restrictive dermopathy, limb-girdle muscular dystrophy, and mandibulo-acral dysplasia." (PMID 23766565, 2013). "1B Limb-girdle muscular dystrophy (LGMD1B), associated with LMNA mutations, also affects the skeletal and cardiac muscles." (PMID 30934932, 2019). "Complex phenotype comprised of limb-girdle muscular dystrophy (LGMD) with atrial fibrillation and tachy-brady syndrome, features of FPLD, short stature and facial dysmorphy was described by Mercuri in a patient with mutation p.E358K in exon 6 of the LMNA gene." (PMID 27585670, 2017). "Mutations in nuclear envelopes, emerin (Emd) and lamin A/C (Lmna) genes, cause clinically indistinguishable myopathy called Emery-Dreifuss muscular dystrophy (EDMD) and limb-girdle muscular dystrophy." (PMID 31430335, 2019).
atrial fibrillation (15 papers, 2010 to 2025). A disorder characterized by an electrocardiographic finding of a supraventricular arrhythmia characterized by the replacement of consistent P waves by rapid oscillations or fibrillatory waves that vary in size, shape and timing and are accompanied by an irregular ventricular response. "Similar to other missense variants, the LMNA p.S143P variant is associated with early-onset progressive AV block, atrial fibrillation, and ventricular tachycardia in severe DCM phenotypes." (PMID 39204134, 2024). "As with other LMNA mutations, cardiac conduction system disease was present with atrial fibrillation accompanied by a slow ventricular rate." (PMID 21179469, 2010). "Additionally, our study showed that 23.1% of the patients with LMNA splice mutations concurrently presented with atrial fibrillation, and the latest research has confirmed that atrial fibrillation is related to decreased expression and lateral distribution of Cx43, as well as interstitial fibrosis." (PMID 38259623, 2023). "Previous studies described LMNA and SCN5A variants to increase the risk of atrial fibrillation development, independently to the severity of cardiac dysfunction." (PMID 38473809, 2024). "These AP features may decrease conduction velocity in atrial cardiomyocytes and autorhythmic cells inducing atrial fibrillation, sick sinus syndrome, and AV-block, all clinical findings of the index family carrying LMNA Q517X mutant (results)." (PMID 35846372, 2022).
Werner syndrome (15 papers, 2012 to 2025). "Rare mutations in critical genes, such as LMNA (Pre-lamin-A/C) in Hutchinson–Gilford progeria or WRN (Werner syndrome RecQ helicase) in Werner syndrome, reveal the fibers’ hidden vulnerabilities, exposing nuclear architecture, DNA repair, and transcriptional control as its most sensitive domains." (PMID 41155437, 2025). "In addition, it has been reported DNA damage accumulation and TRF2 degradation in atypical Werner syndrome (adult Progeria) fibroblasts with LMNA mutations." (PMID 33888761, 2021). "They inferred there were at least three distinct clinical types of the disease, with type 1 comprising classical Werner syndrome with pathogenic WRN variants and type 2 group having an earlier age of onset, resembling the LMNA mutant progeroid syndrome." (PMID 37603195, 2024). "LMNA gene mutations cause a wide spectrum of disorders involving muscle, adipose, bone, and peripheral nervous tissues along with premature aging syndromes, e.g., Werner syndrome (WS) and Hutchinson–Gilford progeria syndrome (HGPS)." (PMID 30781626, 2019). "Likewise, lamin A (LMNA) deficiency and the depletion of the DNA repair gene WRN, which occurs in Werner Syndrome (WS) and causes premature aging, leads to H3, SETDB1, SUV39H1 and HP1 deregulation, contributing to heterochromatin loss and DNA damage." (PMID 40886198, 2025). "The best-studied PSs are Werner Syndrome (WS), Ataxia Telangiectasia (AT) and Hutchinson Gilford Progeria (HGPS), which carry causal mutations in the WRN RecQ helicase, ataxia telangiectasia checkpoint kinase ATM, and lamin A/C respectively." (PMID 25214013, 2015).
Charcot-Marie-Tooth disease (14 papers, 2013 to 2025). An inherited degenerative disorder involving the peripheral nerves. "For example, our model correctly classified all 14 pathogenic variants for Charcot-Marie-Tooth disease, despite their being spread in different genes (LMNA, MFN2 and GARS1)." (PMID 41155097, 2025).
diabetes (14 papers, 2011 to 2024). "One study has shown that heterozygous rare missense mutations in LMNA gene encoding nuclear lamin A/C in diabetes patients are associated with severe metabolic alterations, such as hypertriglyceridemia and insulin resistance." (PMID 33348610, 2020). "This study details the clinical and cellular phenotypes associated with two missense heterozygous mutations in LMNA, c.1745G>T p.(Arg582Leu), and c.1892G>A p.(Gly631Asp), in two patients with early onset of diabetes mellitus, hypertriglyceridemia and non-alcoholic fatty liver disease." (PMID 32012908, 2020). "The obesity and diabetes genes fat mass and obesity-associated (FTO), carnitine palmitoyl transferase 1A (CPT1A), leptin receptor (LEPR), and lamin A/C (LAMIN) genes were significantly down-regulated in the cardamom group." (PMID 38558676, 2024). "Patients with the typical FPLD2 phenotype associated with LMNA p.Arg482 variants are at risk of early atherosclerosis, which can develop even in the absence of diabetes, sometimes before the age of 45." (PMID 35440056, 2022). "Several specific genes in this region, such as LMNA, NOS1AP and ATF6, were identified that they might confer risk for diabetes in some populations." (PMID 21211013, 2011). "The PAD gene list relates to a diverse set of human diseases, including cardiovascular (LMNA, MYH7), cystic fibrosis (CFTR), diabetes (HNF4A, IRS1) and migraine (ATP1A2)." (PMID 25611800, 2015). "Eight (38%) individuals (GCK [four], WFS1 [two], HNF1B [one] and LMNA [one]) had been diagnosed with monogenic diabetes during their clinical follow-up, irrespective of our study." (PMID 36418577, 2023).
neuropathy (14 papers, 2009 to 2025). A disorder affecting the nervous system that manifests with pain, tingling, numbness, and/or muscle weakness. "Given that mutations in human LMNA also produce neuropathies we tested for central nervous system effects using the pan-neural driver elav." (PMID 19855837, 2009). "In addition, a small number of patients (8%), having a myopathy due to LMNA mutation, may show unspecific nerve involvement, mainly axonal, although it is still not clear if the neuropathy is coincidental or pathologically related to LMNA mutations." (PMID 33923914, 2021). "In addition, a small amount of patients (8%), having a myopathy due to LMNA mutation, may show unspecific nerve involvement, mainly axonal, although it is still not clear if the neuropathy is coincidental or pathologically related to LMNA mutations." (PMID 27529282, 2016).
AV block (13 papers, 2015 to 2024). "One third of cases of DCM with AV block are due to LMNA mutations, and nearly two thirds of individuals will have some degree of AV block within 7 years of a diagnosis of LMNA cardiomyopathy." (PMID 39519012, 2024). "Six percent of DCM patients have LMNA mutations, and 33% of DCMs with AV block have LMNA mutations." (PMID 38256355, 2024). "DCM patients with mutations in LMNA, PLN, RBM20, FLNC, DES, or SCN5A are associated with typical cardiac rhythm disorders ranging from atrioventricular blocks to supraventricular and malignant ventricular arrhythmias (MVA)." (PMID 39070560, 2024). "Their report indicates that LMNA mutations can mimic SMA and some patients have cardiac diseases such as atrioventricular block and DCM." (PMID 25886484, 2015). "We report a novel LMNA mutation in a patient with juvenile-onset SMA-like gait disturbance, combined with cardiac diseases including atrioventricular block and cardiac hypofunction with family history of sudden death." (PMID 25886484, 2015).
Insulin resistance (13 papers, 2005 to 2025). Increased resistance towards insulin, that is, diminished effectiveness of insulin in reducing blood glucose levels. "Our work has shown that two heterozygous rare missense mutations in LMNA are associated with severe metabolic alterations, such as hypertriglyceridemia and insulin resistance, and are associated with premature senescence at the cellular level." (PMID 32012908, 2020). "One such syndrome is caused by mutations in the lamin A/C (LMNA) gene, which also has been implicated in familial insulin resistance." (PMID 16262891, 2005). "Importantly, we find that myeloid cell-specific lamin A/C deficiency ameliorates obesity-induced insulin resistance and adipose tissue inflammation." (PMID 29731750, 2018). "Conversely, increased expression of lamin A/C mRNA and protein, seen in adipose tissue macrophages, is proposed to contribute to obesity-induced insulin resistance by affecting NF-kB signaling in myeloid cells." (PMID 37936983, 2023). "We also show that lamin A/C regulates proinflammatory responses via NF-κB activity and myeloid-specific lamin A/C deletion improves obesity-induced inflammation and insulin resistance." (PMID 29731750, 2018). "Given that lamin A/C was elevated in obese adipose tissue and lamin A/C regulated inflammation in macrophages, we then examined the role of myeloid cell lamin A/C in the development of obesity-induced inflammation and insulin resistance." (PMID 29731750, 2018). "In previous studies, lamin A/C has been shown to mediate the activation of adipose tissue macrophage inflammation by regulating the proinflammatory factors, such as NF-κB, or TNFα, contributing to the development of insulin resistance." (PMID 32012908, 2020). "In addition, insulin resistance is an important pathological mechanism in endometrial cancer and EM, and mutations in LMNA are thought to be a causal factor in non-valvular atrial fibrillation (NVAF) and Hutchinson–Gilford premature senescence syndrome (HGPS)." (PMID 37860112, 2023). "Moreover, myeloid-cell-specific lamin A/C depletion ameliorates obesity-induced insulin resistance and reduces adipose tissue inflammation, suggesting that macrophage-expressed lamin A/C contributes to the development of obesity-induced inflammation and insulin resistance." (PMID 32854281, 2020). "Our results show that lamin A/C expression was upregulated in ATMs and played a role in the production of proinflammatory genes, which immediately raises a question whether lamin A/C upregulation in ATMs contributes to the development of the obesity-induced inflammation and insulin resistance." (PMID 29731750, 2018). "Changes in the hypermethylation status of the CpG islets of the laminin A/C (LMNA) gene are associated with insulin resistance in patients with polycystic ovary syndrome (PCOS), suggesting that this gene may be involved in the regulation of PCOS-associated insulin resistance." (PMID 37860112, 2023).
breast carcinoma (12 papers, 2015 to 2023). "Nevertheless, in correlation with their growth disadvantage inside the lung parenchyma, lamin A/C knockdown melanoma and breast cancer cells exhibited markedly reduced growth inside spheroid assemblies." (PMID 34069191, 2021). "In addition, it has been revealed that the expression and function of LMNA were aberrant in several cancers, such as colorectal cancer, liver cancer, brain cancer, and breast cancer." (PMID 35591851, 2022). "Besides, a previous study reported that the mRNA ratio of Lamin C and Lamin A was increased in all clinical stages of breast cancer and the splicing switch of Lamin A/C alternative splice variants may be of diagnostic use." (PMID 33287830, 2020). "In addition, we also showed that loss of nesprin-2 and lamin A/C protein expression was associated with specific clinicopathological characteristics, suggesting that loss of LINC complex proteins plays a pathological role in breast cancer progression." (PMID 26175118, 2015). "Prognostic analyses further revealed that LMNA, LMNB1, and LMNB2 expression all had prognostic value in the distant metastasis‐free survival (DMFS) of breast cancer patients." (PMID 37218524, 2023).
restrictive dermopathy (12 papers, 2012 to 2024). "Restrictive dermopathy (RD) is caused by the autosomal recessive gene defect of ZMPSTE24 or a homozygous classical mutation in the LMNA gene, resulting in an accumulation of a farnesylated and methylated prelamin A." (PMID 35656549, 2022). "Altogether, only 17 genes were primarily identified in relation to cervical insufficiency, with six being syndromic, i.e. COL1A1 and COL3A1 causing EDS; FBN1 causing Marfan syndrome; ZMPSTE24 and LMNA causing restrictive dermopathy; and MATR3 causing myopathy." (PMID 32214361, 2020). "It should be pointed out that two mutations in the LMNA gene result in another severe disorder called restrictive dermopathy (RD)." (PMID 30691039, 2019). "Patients with the laminopathy, restrictive dermopathy (RD), have mutations in either ZMPSTE24 or LMNA, the latter associated with altered processing and the accumulation of prelamin A." (PMID 36260869, 2022).
atherosclerosis (10 papers, 2015 to 2026). A disease characterized by the build-up of fatty material and calcium deposition in the arterial wall resulting in partial or complete occlusion of the arterial lumen. "Hutchinson Gilford progeria syndrome is a fatal disorder characterized by accelerated aging, bone resorption and atherosclerosis, caused by a LMNA mutation which produces progerin, a mutant lamin A precursor." (PMID 26359359, 2015). "Of note is the Lamin A (LMNA) transcript, which is the target of germline mosaic mutations in Hutchinson-Guilford Progeria, a premature aging syndrome characterized by aggressive atherosclerosis and myocardial infarction in adolescents." (PMID 34479557, 2021). "Critically, overexpression of METTL14-N consistently attenuates atherosclerosis progression in vitro and in vivo by disrupting the LMNA-METTL14 signaling pathway." (PMID 41510160, 2026). "Our findings reveal a novel regulatory axis in which sno-circCNOT1 mediated LMNA stabilization, providing mechanistic insights into how LMNA dysregulation contributes to atherosclerosis progression." (PMID 41510160, 2026). "Third, although our in vitro and in vivo experiments demonstrate that sno-circCNOT1 promotes atherosclerosis progression through the LMNA/METTL14 /NLRP3 axis, its clinical significance remains to be fully elucidated." (PMID 41510160, 2026). "Thus, ZMPSTE24 down-regulation, resulting from LMNA mutations or PI treatments, should be considered as a major contributor in VSMC dysfunctions in early atherosclerosis." (PMID 29270905, 2017). "In conclusion, our findings demonstrate that shear-sensitive sno-circCNOT1 promotes endothelial pyroptosis and inflammation via the LMNA/METTL14/NLRP3 axis, thereby accelerating atherosclerosis progression." (PMID 41510160, 2026). "Out of 249 genes in significant modules that were not enriched in pathways or networks, four genes, LMNA and MMP12 at baseline, NPY and RXRA in females and males at 2y have previously been shown to be associated with atherosclerosis." (PMID 35925965, 2022).
conduction disorders (9 papers, 2010 to 2024). "Young patients with DCM, conductive system disorders and skeletal myopathy should be alert to the possibility of LMNA gene variant." (PMID 32962641, 2020). "The Lamin A/C (LMNA) gene variants have been identified to be associated with DCM, conductive system disorders, type 2 Emery-Dreifuss muscular dystrophy and several other disorders." (PMID 32962641, 2020). "Lamin A/C gene (LMNA) mutations have been causally linked to dilated cardiomyopathy (DCM), accounting for 6% to 8% of all idiopathic DCM up to 40% when conduction disorders are present." (PMID 20307303, 2010). "Rare variations in 5 genes were linked to conduction disorders (SCN5A, LMNA, SMAD6, HSPB9, TMEM95)." (PMID 38390584, 2024). "Nucleotide transitions in Lamin A/C, encoded by LMNA with unknown mechanisms, cause DCM and conduction system disorders." (PMID 35527250, 2022).